CCND1 (cyclin D1)
Diseases named in the same sentence as CCND1 in open-access papers (continued):
Sharing a sentence is not in itself a finding about the gene and the disease.
chordoma (3 papers, 2017 to 2022). Chordomas are rare malignant tumors arising from embryonic remnants of the notochord in axial skeleton.
clear cell sarcoma of kidney (3 papers, 2019 to 2025). A rare pediatric sarcoma affecting the kidney. "BCOR-ITD and YWHAE-rearranged tumors define an infantile SRCS subset with truncal/abdominopelvic predilection, aggressive behavior, and characteristic immunophenotypes (BCOR, cyclin D1, SATB2), overlapping morphologically with clear cell sarcoma of the kidney." (PMID 41514642, 2025).
Cognitive impairment (3 papers, 2014 to 2024). Abnormal cognition is characterized by deficits in thinking, reasoning, or remembering. "In this respect, we evaluated the long-term effect of PRM and LCM, administered singly in a high-dose or in a low-dose combination of both on comorbid anxiety, cognitive impairment, BDNF, and Cyclin D1 hippocampal expression in an experimental model of TLE." (PMID 39727966, 2024).
diabetic nephropathy (3 papers, 2021 to 2023). "LncRNA SNHG16 promotes proliferation and fibrogenesis by downregulating miR-141-3p expression and upregulating CCND1 expression in diabetic nephropathy." (PMID 33977869, 2021). "Besides, SNHG16 could induce proliferation and fibrogenesis via modulating miR-141-3p and CCND1 in diabetic nephropathy." (PMID 34290731, 2021).
ductal carcinoma (3 papers, 2013 to 2021). "Also, Ravikumar and Ananthamurthy showed that high cyclin D1 expression was identified 67.5% in ductal carcinoma." (PMID 34089425, 2021).
endometrial endometrioid carcinoma (3 papers, 2008 to 2019). "Here, we demonstrate that CCND1 mutations are of very low frequency across the vast majority of cancer types (0.5%, 151 of 29,432 cases), but are predominantly enriched in endometrial endometrioid carcinomas in both the primary and metastatic settings (6.5%, 30 of 458 cases)." (PMID 29969496, 2018). "For example, of single-base substitutions in the CCND1 gene changing proline-287 (Pro-287) to a serine or threonine residue in endometrioid endometrial carcinoma correlates with overexpression of cyclin D1 in the nucleus of neoplastic cells." (PMID 18764945, 2008).
endometrial tumors (3 papers, 2012 to 2025). "Furthermore, treatment of Lkb1fl/flp53fl/fl transgenic mice with linoleic acid for four weeks significantly reduced the growth of endometrial tumors and decreased the expression of VEGF, vimentin, Ki67, and cyclin D1 in tumor tissues." (PMID 38465855, 2024).
epithelial dysplasia (3 papers, 2007 to 2023). "Our results showed elevated cyclin D1 expression in the epithelial dysplasia." (PMID 17922924, 2007). "Epithelial dysplasia and OSCC showed increased levels of cyclin D1, with the highest levels seen in the OSCC group." (PMID 37109048, 2023).
Infertility (3 papers, 2018 to 2026). "Four transcription regulators (CCND1, FOXO1, CREB1, and HDAC4) were found to be targeted by DE-miRNAs, suggesting that they could be critical regulators in events associated with EMS and may play a role in infertility." (PMID 38002087, 2023).
injury (3 papers, 2011 to 2024). Damage inflicted on the body as the direct or indirect result of an external force, with or without disruption of structural continuity. "In this study, we found that the HuR protein expression was inducible in the mouse model of APAP‐induced liver injury and found that HuR could protect against APAP‐induced liver injury by promoting the expression of NRF2, cyclin A1, cyclin B1, cyclin D1, CDK2, ATG3, ATG5 and ATG7." (PMID 39614424, 2024).
invasive lobular carcinoma (3 papers, 2008 to 2021). "The majority of invasive lobular carcinomas showed cyclin D1 overexpression at the protein levels, suggesting its role in the progression of invasive lobular carcinoma." (PMID 33920506, 2021). "Moreover, data from another study indicated amplification of the cyclin D1 gene and noted its correlation with ER-positive invasive lobular breast carcinoma with lymph node metastasis, suggesting a sign of poorer prognosis." (PMID 33920506, 2021). "Although initial studies had suggested the cyclin D1 was overexpressed in invasive lobular carcinoma but not LCIS, more recent studies have shown up regulation of cyclin D1 in LCIS." (PMID 18954444, 2008).
larynx cancer (3 papers, 2018 to 2022). A primary or metastatic malignant neoplasm involving the larynx. "Furthermore, associated with the existence of LSCC located in the supraglottic larynx, highly invasive (T3 and T4) malignant neoplasms of the larynx and tumors being at an advanced clinical stage (III and IV) are CCND1 immunopositivities." (PMID 29443735, 2018).
leukoplakia (3 papers, 2007 to 2025). A white patch or plaque on a mucous membrane that cannot be characterized clinically or pathologically as any other disease. "This has been demonstrated in IHC studies where Cyclin D1 expression is most frequently associated with oral leukoplakia compared to the normal oral mucosa, and the pRb-/Cyclin D1+ phenotype is associated with transition from premalignant to malignant lesions." (PMID 41465166, 2025). "Cyclin D1 was intensely expressed in the oral leukoplakia where nuclear expression of β-catenin is evident, in contrast to those without nuclear expression of β-catenin." (PMID 17922924, 2007). "Furthermore, Kovesi and Szende reported that expression of cyclin D1 increased during progression of the severity in oral leukoplakia." (PMID 17922924, 2007).
malignant peripheral nerve sheath tumor (3 papers, 2016 to 2018). Malignant peripheral nerve sheath tumor (MPNST) is a rare and often aggressive soft tissue sarcoma occurring in a wide range of anatomical sites. "Studies showed that JQ1 or BRD4 knockdown in NF1 (Neurofibromatosis type 1)-associated malignant peripheral nerve sheath tumors decreased the expression of CCND1." (PMID 26830473, 2016).
marginal zone lymphoma (3 papers, 2023 to 2025). A usually indolent mature B-cell lymphoma, arising from the marginal zone of lymphoid tissues. "In this case, despite CD23 negativity, CD43, CD200, and LEF1 positivity support the diagnosis of CLL/SLL, whereas cyclin D1 and SOX11 negativity and LEF1 positivity exclude mantle cell and marginal zone lymphoma, respectively." (PMID 40893576, 2025). "Differential diagnosis for marginal zone B cell lymphoma mainly depends on immunohistochemistry, including at least CD20, CD10, CD5, CD23, cyclin D1, immunoglobulin D, and SOX11." (PMID 36973717, 2023).
medullary thyroid carcinoma (3 papers, 2017 to 2023). "The largest proportion of cases with high CCND1 CN was found among medullary carcinomas and Luminal B (HER2−) tumours." (PMID 35459982, 2022). "The highest proportion of cases with high CCND1 CN was seen among medullary carcinomas (5/13; 38%)." (PMID 35459982, 2022). "In medullary thyroid carcinoma (MTC)-derived cells, metformin reduced the expression of cyclin D1 and inhibited cell growth." (PMID 37773165, 2023).
myelodysplastic syndrome (3 papers, 2015 to 2018). A clonal hematopoietic disorder characterized by dysplasia and ineffective hematopoiesis in one or more of the hematopoietic cell lines. "ON01910.Na is now undergoing phase III clinical trials for myelodysplastic syndromes (MDS) correlated with misexpression of cyclin D1." (PMID 26557691, 2015). "In myelodysplastic syndrome (MDS) cells (SKM-1 cells), ART regulates apoptosis by inhibiting the expression of downstream targets of Wnt/β-catenin signaling pathway, such as c-Myc and cyclin D1." (PMID 30326962, 2018).
myeloid leukemia (3 papers, 2016 to 2024). A clonal proliferation of myeloid cells and their precursors in the bone marrow, peripheral blood, and spleen. "The pathways and genes that significantly changed were classified as follows: cancer pathways (EPAS1, CCND1, FGF13), myeloid leukemia pathways (ZBTB16, KIT, IL13), hematopoietic cell lineage pathways (EPOR, GYPA, CD36) and so on." (PMID 27516205, 2016).
parathyroid hyperplasia (3 papers, 2020 to 2025). A hyperplasia that involves the parathyroid gland. "Occasional overexpression of the cyclin D1 (CCND1), formerly proto-oncogene PRAD1, has been identified in parathyroid hyperplasia in uremic patients, suggesting a possible neoplastic component in long-standing secondary or tertiary hyperparathyroidism." (PMID 41211056, 2025).
Parkinson disease (3 papers, 2019 to 2023). A progressive degenerative disorder of the central nervous system characterized by loss of dopamine producing neurons in the substantia nigra and the presence of Lewy bodies in the substantia nigra and locus coeruleus. "Moreover, mitogenic markers such as Proliferating Cell Nuclear Antigen, pRb, cyclins, and CDKs have been found in CNS samples of Alzheimer’s and Parkinson’s disease patients while Huntington’s disease and ALS patients demonstrated elevated CNS levels of pRB and cyclin D1." (PMID 31369591, 2019).
pheochromocytoma (3 papers, 2016 to 2024). "miR-15 and miR-16 were raised as potential therapeutic targets, as their restoration in expression promoted cell death, partly through the down-regulation of CCND1 (Cyclin D1) in metastatic rat pheochromocytoma cells." (PMID 33810219, 2021). "The absence of consistent clinical manifestations and test results throughout the disease process of von Hippel Lindau syndrome due to CCND1 gene mutations suggests that the correlation between this specific mutation and the onset of pheochromocytoma was not present in this case." (PMID 38835385, 2024). "Additionally, raised expression of REST in pheochromocytoma cell line could increase oncogenes Myc and CCND1, which might account for the proliferation advantage and the distinct morphology." (PMID 27153061, 2016).
pineoblastoma (3 papers, 2009 to 2016). Pineoblastoma is a rare, malignant type of supratentorial primitive neuroectodermal tumor (sPNET), found mainly in children (less than 10% of cases are reported in adults), and located in the pineal region of the brain but that can metastasize along the neuroaxis. "Our model of cyclin D1-driven pineoblastoma most closely resembles human sPNET, where cyclin D/CDK amplifications are frequent." (PMID 26598601, 2016). "CCND1 was overexpressed in 12 samples (44%, no pineoblastomas) with percentages of positive cells ranging from 11 to 56%." (PMID 19293793, 2009).
preeclampsia (3 papers, 2017 to 2022). Preeclampsia is a hypertensive disorder of pregnancy that is characterized by new-onset hypertension with proteinuria presenting after 20 weeks of gestation, and depending on mild or severe forms may initially present with severe headache, visual disturbances, and hyperreflexia. "It has been found that in the process of placentation, if adverse pregnancy occurs, the expression of CCND1 is upregulated, such as in preeclampsia." (PMID 36230445, 2022). "As a type of miRNA, roles of miR-155 in preeclampsia were investigated in several previous studies, and were reported to be elevated in preeclampsia and regulate eNOS, cyclin D1, and CYR61 expression levels in placenta." (PMID 36153499, 2022). "In relation to the cell cycle and proliferation, evidence shows that CCND1 is decreased in placentas from IUGR and preeclampsia complicated with IUGR, while CDKN1A is increased in IUGR placentas." (PMID 28380025, 2017).
renal oncocytoma (3 papers, 2010 to 2022). "In another study, CCND1 was found to be a useful immunohistochemical marker to discriminate between chromophobe renal cell carcinoma and renal oncocytoma." (PMID 32013938, 2020).
rheumatoid arthritis (3 papers, 2014 to 2024). A chronic, systemic autoimmune disorder characterized by inflammation in the synovial membranes and articular surfaces. "Now, we reported that thapsigargin dramatically reduced the transcription and translation of cyclin D1 in MH7A human rheumatoid arthritis synovial cells." (PMID 24688409, 2014). "Our work highlights an important role of cyclin D1 in the proliferation and apoptosis in rheumatoid arthritis and sets a stage to the clinical treatment of rheumatoid arthritis by thapsigargin." (PMID 24688409, 2014). "Our findings highlight important roles of cyclin D1 in the proliferation and apoptosis in rheumatoid arthritis and set a stage to the clinical treatment of rheumatoid arthritis by thapsigargin." (PMID 24688409, 2014). "Our findings highlight important roles of cyclin D1 in the proliferation and apoptosis in rheumatoid arthritis and set a stage to the molecular mechanism of FLS proliferations and the clinical treatment of rheumatoid arthritis by thapsigargin." (PMID 24688409, 2014).
T cell lymphoma (3 papers, 2012 to 2025). "In this case report we underline the diagnostic pitfall rapresented by Cyclin D1 immunoistochemical overexpression in a T-cell lymphoma." (PMID 22770229, 2012).
tongue SCC (3 papers, 2014 to 2025). "In the subgroup meta-analysis, the strength of association of cyclin D1 expression in tongue SCC was stronger than in mixed tumor sites of the oral cavity." (PMID 24675814, 2014). "Suitably, the present study showed that 80% of T3/T4 cases had significantly higher Cyclin D1 and Ki-67 expression, what serve as a useful link between the clinical and histopathological appearance of tongue SCCs." (PMID 26449430, 2015). "In conclusion, tumors presenting higher T stages and poor prognosis also presented higher Cyclin D1 and Ki-67 staining, what enforces these biomarkers as an auxiliary tool to predict the progression of tongue SCC at the time of diagnosis." (PMID 26449430, 2015). "The immunohistochemical expression of Cyclin D1 and Ki-67 were analyzed in tongue squamous cell carcinomas (SCC), relating them to the clinical and morphological exhibition of these tumors." (PMID 26449430, 2015). "Ki-67 and Cyclin D1 pose as auxiliary tools when determining the progression of tongue SCC at the time of diagnosis." (PMID 26449430, 2015). "Thus, this study aimed to evaluate the expression of Cyclin D1 and Ki-67 within tongue SCCs to correlate this expression to the clinical appearance and behavior of the tumors." (PMID 26449430, 2015). "There may be two reasons for this difference: First, compared to other subsites in the oral cavity, tongue SCC is characterized by a more aggressive biological phenotype, with a high-degree of cervical lymph node spread that might be reflected at molecular level, such as with cyclin D1 expression." (PMID 24675814, 2014).
tongue tumor (3 papers, 2017 to 2025). "Morphometric and immunohistochemical analysis found that P. gingivalis chronic infection markedly enhanced the severity of the tongue tumours; STAT3 controls crucial genes driving proliferation, suppression of apoptosis, and aggressive tumour behaviour through the upregulation of cyclin D1." (PMID 41228271, 2025).
ulcerative colitis (3 papers, 2020 to 2023). An inflammatory bowel disease involving the mucosal surface of the large intestine and rectum. "Aspirin remarkably decreased phosphorylated-STAT3, signal transducer and activator of transcription, and cyclin D1 expression compared with ulcerative colitis model group (P < .05)." (PMID 35946886, 2022). "The expression of phosphorylated-STAT3, signal transducer and activator of transcription 3, cyclin D1, and suppressor of cytokine signaling 3 was significantly increased in mice of ulcerative colitis model group compared to the control group (P < .05)." (PMID 35946886, 2022). "In addition, the watermelon augmentation decreased the levels on cyclin D1, a vital protein in the Wnt signaling pathway in the high fat fed mice with ulcerative colitis." (PMID 33187365, 2020). "Elevated expression of cyclin D1 is widely observed in ulcerative colitis and colon carcinogenesis." (PMID 33187365, 2020).
uterine tumor (3 papers, 2017 to 2021). "She had a 90 mm uterine tumor, microscopically composed of ovoid cells with a myxoid background, low mitotic count, no tumor necrosis and no vascular invasion, strongly positive for CD10 and Cyclin D1, weakly positive for hormone receptors." (PMID 32933053, 2020).
vitiligo (3 papers, 2013 to 2021). Generalized well circumscribed patches of leukoderma that are generally distributed over symmetric body locations and is due to autoimmune destruction of melanocytes. "In parallel, 3MA-treated vitiligo fibroblasts showed a decreased Cyclin D1 expression, thus suggesting an arrest in cell cycle progression." (PMID 33767135, 2021).
vulvar cancer (3 papers, 2021 to 2022). "In a study of 183 patients with vulvar cancer, CCND1 was detected to be overexpressed in vulvar cancer tissues of most patients." (PMID 35893031, 2022). "After functional annotation, FGF19 and CCND1, involved in the development of the reproductive tract, cell growth and vulvar cancer, were identified as the possible candidate genes of vulvar traits." (PMID 35893031, 2022). "In vulvar cancer, CCND1 overexpression has been shown to be significantly related to the presence of regional lymph node metastases (p < 0.001) and HPV negativity (p < 0.001)." (PMID 34944992, 2021). "In this refined region, FGF19 and CCND1, involved in the development of the reproductive tract, cell growth and vulvar cancer, could be new candidate genes affecting VL." (PMID 35893031, 2022).
acromegaly (2 papers, 2022). Acromegaly is an acquired disorder related to excessive production of growth hormone (GH) and characterized by progressive somatic disfigurement (mainly involving the face and extremities) and systemic manifestations. "Differences between transcriptomic groups were also observed in expression levels of proliferation-related genes CCND1, CDKN1B, and MKI67 and genes involved in cell signaling TGFB1 and STAT3 that all have a reported role in acromegaly patients’ outcome." (PMID 36497102, 2022).
acute monocytic leukemia (2 papers, 2015 to 2025). Acute monoblastic leukemia (AML-M5), is one of the most common subtypes of acute myeloid leukemia (AML) that is either comprised of more than 80% of monoblasts (AML-M5a) or 30-80% monoblasts with (pro)monocytic differentiation (AML-M5b). "Cyclin D1 is an initiator and activator of the cell cycle and is overexpressed in a wide range of types of human tumor, includin acute monocytic leukemia." (PMID 26136223, 2015).